GREB1 (growth regulating estrogen receptor binding 1)
Diseases named in the same sentence as GREB1 in open-access papers (continued):
Sharing a sentence is not in itself a finding about the gene and the disease.
tumor (continued). "We therefore analysed the expression of the ER-regulated genes (ERGs) TFF1, GREB1 and PR, together with PLK1, Ki67, PCNA and CENPE (a centromere associated protein that accumulates in G2 phase and is involved in chromosome alignement), in treated tumours." (PMID 32792481, 2020). "Therefore, GREB1 is involved in HB-like histological patterns, marker gene expression, and tumor formation in this mouse model." (PMID 31462641, 2019). "Indeed, GREB1 ASOs suppressed HepG2-induced xenograft liver tumor formation and HB-like tumor formation in BYM model mice as well as inhibiting GREB1 expression." (PMID 31462641, 2019). "Furthermore, Smad2/3 knockout rescued impaired cell proliferation in vitro and xenograft tumor formation by GREB1 knockout, suggesting that GREB1 abrogates TGFβ signal-dependent inhibition of cell proliferation." (PMID 31462641, 2019). "Given that GREB1 expression is highest in dysplastic OSE and FTE, this suggests that GREB1 may play a role in the initiation of tumour formation in both cell types." (PMID 30418965, 2018). "However, GREB1 overexpression accelerated tumour growth; average tumour weight at endpoint was 4.5-fold higher in mice engrafted with GREB1-overexpressing cells vs. control cells." (PMID 29973689, 2018). "Amplification of GREB1, an early response gene in the estrogen receptor‐regulated pathway, may play a role in this estrogen receptor positive tumor." (PMID 26432421, 2015). "GREB1 protein was expressed in tumor epithelial cells and CAFs." (PMID 22359603, 2012). "Hence the regulation of GREB1 expression by LRH-1 identifies a novel mechanism for tumor cell proliferation." (PMID 22359603, 2012). "Moreover, the results of our study suggest that tumors with CTNNB1 mutation and GREB1::CTNNB1 fusion may exhibit identical morphology and potentially represent the same category of tumor." (PMID 41606383, 2026). "Recently, it has also been proposed that GREB1 expression is highest in murine dysplastic ovarian surface epithelial and fallopian tube epithelium, suggesting that GREB1 may play a role in the initiation of tumor formation in both cell types." (PMID 32549322, 2020). "These gene fusions, such as GREB1::NCOA2 and ESR1::NCOA2, result in the aberrant activation of estrogen signaling pathways, driving the proliferation and survival of tumor cells." (PMID 38276058, 2024). "The high GREB1 and MITF expression levels were significantly correlated with pathological T factor (pT), which reflects the tumor thickness." (PMID 37658191, 2023). "LRH-1 expression is positively correlated with tumor ERα status and here we demonstrate a co-operative effect of LRH-1 and ERα on GREB1 expression and cell proliferation." (PMID 22359603, 2012). "Multivariate Cox regression analyses showed that only PR and GREB1 are predictors of ET response independent of tumour grade, size or lymph node status." (PMID 40937605, 2025). "Furthermore, GREB1 ASO-5715 targeting mouse GREB1 mRNA tended to inhibit liver tumor formation in BYM mice and also suppressed GREB1 expression in tumor cells." (PMID 31462641, 2019). "The GREB1 mRNA level in individual tumor nodule was higher than that in the nontumor regions and normal liver tissue." (PMID 31462641, 2019). "Tumour weight at endpoint was not altered by GREB1 knockdown, implying that the knockdown slowed tumour growth." (PMID 29973689, 2018). "In fact, 81% of ESR1− and 78% of ESR1+ tumours were GREB1+ by IHC, with no major differences across subtypes." (PMID 29973689, 2018). "In vivo, GREB1 knockdown in tumours decreased survival, but surprisingly, overexpression did not alter survival." (PMID 29973689, 2018). "In the tumor lesions, GREB1 mRNA was significantly upregulated compared with the nontumor regions." (PMID 31462641, 2019). "Targeting GREB1 may inhibit tumour-promoting pathways both downstream and independent of ESR1 and is therefore a possible treatment strategy worthy of further investigation." (PMID 29973689, 2018).
tumor (continued). "In contrast, 5 of the 20 clear cell tumours examined were negative for both GREB1 and ESR1." (PMID 29973689, 2018). "However, it remains unclear whether GREB1 expression is involved in tumor formation in cancers that are not hormone-sensitive." (PMID 31462641, 2019). "Knockdown of GREB1 by shRNA in BYM mice (BYM GREB1 KD mice) (K1-K6), resulted in reduced tumor formation, and no tumors were present in four out of the six mice." (PMID 31462641, 2019). "Expression of GREB1 and DLK1 in the tumor lesions was higher than the nontumor regions, and their staining levels were correlated with the degree of differentiation." (PMID 31462641, 2019). "Nearly all of the 60 serous, mucinous, and endometrioid tumours examined were positive for either GREB1 or ESR1 (or both); only one tumour was negative for both markers, and notably, ESR1 staining was still observed in one of three scoreable cores from this tumour." (PMID 29973689, 2018).
cancer (27 papers, 2007 to 2024). A tumor composed of atypical neoplastic, often pleomorphic cells that invade other tissues. "GREB1 transcripts of Breast-BRCA and Prostate-PRAD primarily encoded full-length GREB1, but GREB1 mRNA transcription levels were low in other cancers." (PMID 37658191, 2023). "Previous studies have demonstrated that GREB1 played an important role in hormone-responsive tissues and cancer." (PMID 39596826, 2024). "The top enriched GO terms among genes suppressed by GREB1 included circadian regulation of gene expression, the dysregulation of which affects various hallmarks of cancer, as well as serine phosphorylation and autophagy." (PMID 37611092, 2023). "Together, these findings strongly point to MYO1B as a transcriptional target of GREB1 in NB and other cancers." (PMID 37611092, 2023). "Together, these findings further support the notion that GREB1 mediates the pathobiological consequences of MNA in at least some distinct cancers, including both NB and MB." (PMID 37611092, 2023). "Among the top 5% of DEGs most significantly changed, we found Prtg, Lin28, Greb1, and Irs2, known as positive regulators of cell proliferation upregulated in cancer." (PMID 32985705, 2020). "With a specific role that persists confusion, the expanding evidence suggests that it plays a crucial function in the pathway of hormone responses in cancer cells, as GREB1 suppression diminishes cancer cell growth in in vitro models of cancer." (PMID 32549322, 2020). "Beyond the cancer research, one of the growing fields of research involving GREB1 is its role in the BMD and derived its role in osteoporosis, which is a critical manifestation of low BMD." (PMID 32549322, 2020). "Here we show that expression of growth regulation by estrogen in breast cancer 1 (GREB1) depends on Wnt/β-catenin signaling in HB patients." (PMID 31462641, 2019). "By addressing such questions, the field will be able to fully elucidate the normal functions of GREB1, define its role in cancers, and assess its potential as a prognostic and therapeutic target." (PMID 30154312, 2018). "Public databases show that GREB1 mRNA levels are highest in the reproductive tract and in cancers arising from those tissues." (PMID 29973689, 2018). "The pan hormone-responsive gene GREB1 plays important roles in the initiation and progression of some sex hormone-driven cancers." (PMID 30154312, 2018). "Expression of many ERα target genes, including GREB1 (gene regulated in breast cancer 1), PGR (the progesterone receptor gene) and PRLR (the prolactin receptor gene), was induced by oestradiol and blocked by fulvestrant, but only in cells transduced with ERα." (PMID 17573968, 2007). "Although there are no specific data about a role of GREB1 in testicular cancer, it has been associated with testicular functions in murine models, which deserves further study from the cancer research point of view." (PMID 32549322, 2020). "This mini-review examines evidence that GREB1 participates in several hormone-dependent cancers and could be targeted to treat these cancers." (PMID 30154312, 2018). "Another downregulated protein is the growth regulation by estrogen in breast cancer 1 (GREB1)." (PMID 29085821, 2017). "Therefore, GREB1 expression in lower stage receptor-positive cancers might be more favorable toward prognosis." (PMID 30154312, 2018). "While for genes GREB1, TBX4 and CYP24A1, both HMs showed higher signals in cancer cell lines than that in normal cells." (PMID 37426199, 2023). "Many E2 regulated genes in other normal and cancer cell types were also regulated in MOE cells including Pgr, Greb1, Csf2, and Dhrs9, while other E2 regulated genes in MCF7 cells were not regulated (Nrip1) or even expressed (Tff1) in MOE cells." (PMID 26879975, 2016). "We next determined the effects of LRH-1 on estrogen-dependent cancer cell proliferation, and correlated cell proliferation to changes in transcript levels of LRH-1, ERα and GREB1." (PMID 22359603, 2012).
cancer (continued). "All these genes (AREG, GREB1, TFF1 and TFF3) were up-regulated in ER+ carcinomas compared to ER- carcinomas (AREG was only borderline significant)." (PMID 21812955, 2011). "Interestingly, the expression analysis of GREB1 demonstrated in Oncomine, the Cancer Cell Line Encyclopedia (CCLE), and protein atlas indicate that GREB1 has much wider expression than in hormone-related organs or tissues." (PMID 30154312, 2018). "Moreover, we discovered that Greb1, an ERα-regulated gene potentially involved in estrogen action, is induced by E2 via ERα binding to ERE in mouse granulosa cells, as previously demonstrated in cancer cells." (PMID 39570927, 2024). "Metformin treatment reduced GREB1’s expression, which might result with a negative progression of the disease, therefore GREB1 protein can be considered as another target of cancer therapy." (PMID 29085821, 2017).
GREB1 also shares sentences with these, for which no sentence is quoted: adenosarcoma (1 paper); benign prostatic hypertrophy (1); benign tumors (1); carcinoid syndrome (1); clear cell carcinomas (1); endometrial stromal sarcomas (1); female infertility (1); hepatocellular carcinoma (1); leiomyosarcoma (1); lymph node metastasis (1); medulloblastoma (1); mesenchymal tumor (1); metastatic melanoma (1); metastatic tumors (1); migraine (1); prostate adenocarcinoma (1); serous ovarian tumors (1); skeletal system disease (1); undifferentiated sarcoma (1); uterine fibroids (1).